KMT2A (lysine methyltransferase 2A)
Diseases named in the same sentence as KMT2A in open-access papers (continued):
Sharing a sentence is not in itself a finding about the gene and the disease.
leukemia (continued). "It is the first time to unravel the prognostic value of KMT2A expression, but not mutation, in gastric cancer, although KMT2A mutations, including KMT2A-PTD, have been demonstrated as a potential predictor in other cancer, particularly in leukemia." (PMID 38025523, 2023). "Mix lineage leukemia (MLL)/KMT2A-rearranged leukemia represents one of the most refractory acute leukemia subtypes." (PMID 37036970, 2023). "The histone lysine demethylase KDM2A was described to be an opposing regulator of ASH1L by specifically demethylating H3K36me2, which leads to the dissociation of KMT2A/PS1P1 and the decreased description of KMT2A target leukemia genes." (PMID 37296904, 2023). "In both cell lines and patient-derived NPM1c leukemia cells menin inhibition removes the menin-KMT2A complex from target gene loci and suppresses expression of especially MEIS1 and its transcriptional target FLT3." (PMID 38174649, 2023). "Data integration highlighted a phosphoproteomics signature that define two biologically distinct groups of KMT2A rearranged leukaemia, which we term MLLGA and MLLGB." (PMID 36843114, 2023). "Because revumenib disrupts the effect of epigenetic regulators in leukaemia that are dependent on the menin–KMT2A interaction, this leads to abrogation of aberrant gene expression and removal of the haematopoietic differentiation block." (PMID 36922593, 2023). "KMT2A (Mixed Lineage Leukemia, KMT2A, and MLL) rearrangement (KMT2A-r) derived fusion proteins are strong drivers of leukemic transformation." (PMID 38201282, 2023). "Our studies uncover a selective dependency of all KMT2A-complex dependent (KMT2A-r and NPM1c) leukemias, across phenotypic subtypes, on immunoproteasome function." (PMID 38049829, 2023). "MLL‐fusion leukemias are aggressive forms of acute leukemias carrying chimeric fusion of the MLL (also called KMT2A) gene." (PMID 36453131, 2023). "KMT2A::AF4 directly regulates BCL2 gene expression by promoting increased H3K79me2/3 levels in the BCL2 gene vicinity leading to a BH3-dependance in KMT2A-rearranged leukaemia." (PMID 37189994, 2023). "Leukemias harboring translocations involving chromosome 11q23 are characterized by rearrangements of the Mixed-Lineage-Leukemia-gene (MLL1, KMT2A) and result in aberrant regulation of the epigenetic landscape." (PMID 38049829, 2023). "In leukemia patients with NPM1c, or rearrangements in KMT2A and NUP98, a number of these regulators are considered instrumental for loss of transcriptional control and aberrant expression of HOXA/B/MEIS1, and other leukemia-associated target genes." (PMID 38174649, 2023). "In summary, our multilayer molecular profiling of AML with poor prognosis and KMT2A-MLLT3 karyotypes identified a phosphoproteomics signature that defines two biologically and phenotypically distinct groups of KMT2A rearranged leukaemia." (PMID 36843114, 2023). "In leukemia with KMT2A::AFF1 (MLL::AF4) fusions, we previously reported specific alterations of circRNA expression, but nothing was known about f-circRNAs." (PMID 36585787, 2023). "The second highlight of this study came from the investigation of leukemia with the KMT2A::AFF1 (MLL::AF4) fusion." (PMID 36585787, 2023). "Rearrangements of the KMT2A gene drive epigenetic changes that lead to aberrant gene expression profiles that strongly favor leukemia development." (PMID 37686014, 2023). "All three 11q22.3 deletions involving ATM (sizes: 16, 17, and 18 Mb) also encompassed at least two of the other nearby leukemia-associated genes (BIRC3, ZBTB16, KMT2A, or CBL)." (PMID 36831635, 2023). "In particular, rearrangements involving the MLL (or KMT2A) gene, encoding for the histone lysine methyltransferase 2A, are detected in the majority of infant leukemia patients, and specifically in around 75% of ALL and 50% of AML." (PMID 37509285, 2023). "Venetoclax was found to synergize with DOT1L inhibitors and is being evaluated in clinical trials for pediatric KMT2A-rearranged leukemias." (PMID 37740239, 2023).
leukemia (continued). "Very recently a small molecular weight inhibitor has been developed which not only effectively inhibits the growth of cells from leukaemias with a translocation of KMT2A but also reduces the expression of the fusion protein target genes." (PMID 35406676, 2022). "LSD1 plays an important role in maintaining the oncogenic programme in leukaemias, showing a translocation of KMT2A and its inhibitors, which are in the clinic induce differentiation of the leukaemic blast cells." (PMID 35406676, 2022). "Given that the interaction of menin and KMT2A protein is essential in initiating the oncogenesis of HOXA9-driven leukemia, menin-KMT2A inhibitors are promising molecular-targeting agents applicable to a considerable proportion of AML patients." (PMID 35682627, 2022). "For example, leukemias with MECOMr, NUP98r, KMT2Ar, and KMT2A-PTD are being explored as therapeutic targets within clinical trials [NCT04067336; NCT04811560]." (PMID 35915143, 2022). "Fusion genes involving KMT2A are likely sufficient for leukemia development, as suggested by a high concordance rate in monozygotic twins and rare detection of secondary, cooperative mutations." (PMID 35294722, 2022). "In agreement with a prior report, unsupervised clustering of leukemias by superenhancer structure significantly segregated KMT2A-rearranged samples into two related clusters." (PMID 35301220, 2022). "A total of 135 KMT2A rearrangements have been described in leukemias, mostly resulting in KMT2A-fusion proteins capable of transforming hematopoietic stem cells into leukemic blasts with stem cell-like properties." (PMID 36245718, 2022). "In infants with B ALL (<1 year of age), initial KMT2A rearrangements (particularly KMT2A/AFF1 gene fusions) in utero appear to be sufficient for the onset of leukemia before or shortly after birth, although secondary mutations are present in some cases." (PMID 35409034, 2022). "Largely due to the discovery of the translocations of KMT2A-producing fusion proteins in 70% of infant leukaemias and 10% of adult leukaemias, concentrated efforts have been applied to understanding the function of KMT2A in leukemogenesis." (PMID 35406676, 2022). "In this way, a total of 58 leukemia inter-chromosomal fusions were obtained, of which 45 (78%) involve partner gene KMT2A." (PMID 35945623, 2022). "KMT2A was previously known as MLL (Mixed-Lineage Leukemia) because of its recognition as a frequent target of somatic rearrangements in acute leukemia." (PMID 35893049, 2022). "KMT2A-r leukemia is characterized by chromatin remodeling, epigenetic modifications and changes in histone marks." (PMID 35677155, 2022). "The KMT2A gene is a frequent target of rearrangement in human leukemia, especially in infant and pediatric leukemia." (PMID 36213638, 2022). "KMT2A-rearranged acute lymphoblastic leukemia (ALL) in infants (<1 year of age) represents an aggressive type of childhood leukemia characterized by a poor clinical outcome with a survival chance of <50%." (PMID 35327440, 2022). "The availability of FDA-approved potent inhibitors of SRC family PTK such as ponatinib, bosutinib, and dasatinib provides an opportunity to evaluate their clinical impact potential for KMT2A/MLL-R+ leukemias in proof-of-concept clinical trials." (PMID 36627892, 2022). "KMT2A-rearranged infant acute lymphoblastic leukemia (ALL) represents the most refractory type of childhood leukemia." (PMID 36042201, 2022). "The synergistic action of two methylases: KMT2A/MLL1 (methylates H3K4, see next section) and ASH1L (KMT2H), is associated with leukemogenesis and with regulation of HOX gene expression in leukaemias with KMT2A translocations." (PMID 35406676, 2022). "The histone lysine [K]-Methyl Transferase 2A gene (KMT2A), which was formerly known as the mixed-lineage leukemia (MLL) gene, is located on chromosome 11q23." (PMID 35269896, 2022).
leukemia (continued). "Leukemias carrying KMT2A rearrangements formed a single cluster, cosegregating with many leukemias having no major chromosomal rearrangements, which we termed KMT2Ar-like." (PMID 35301220, 2022). "ZNF521 is a critical effector of KMT2A fusion proteins in blocking myeloid differentiation and can be used as a potential therapeutic target for this leukemia subtype." (PMID 36139405, 2022). "MBNL1 is a protein involved in alternative splicing, predominantly regulates intron exclusion, and has been found consistently overexpressed in KMT2A-rearranged leukemia." (PMID 36518527, 2022). "As leukemias are primarily classified by their hematopoietic phenotype, we propose that KMT2A-rearranged infant B-ALL be considered an ELP-like leukemia." (PMID 35288693, 2022). "Using the single-cell Hi-C data and classifying genes based on their statuses in the COSMIC database, we found that leukemia fusion genes tended to colocalize in normal blood cells, with most fusions incorporating KMT2A." (PMID 35945623, 2022). "To uncover the molecular heterogeneity of this disease, we perform RNA sequencing, methylation array analysis, whole exome and targeted deep sequencing on 84 infants with KMT2A-rearranged leukemia." (PMID 36042201, 2022). "The observation that KMT2A-rearranged leukemias are critically dependent on Menin and more particularly the interaction between Menin and KMT2A has prompted the development of small molecule inhibitors of this protein-protein interaction." (PMID 33542482, 2021). "Septin 6 (SEPT6), a member of the septin family of GTPases, which preserves breakpoint at chromosomes Xq24, was found as a fusion partner with Leukemia gene (MLL1 or KMT2A) related to leukemia." (PMID 34926267, 2021). "The DOT1L inhibitor pinometostat showed a modest anti-leukaemic activity in patients with KMT2A-rearranged leukemia in a phase I study." (PMID 34683144, 2021). "We previously found that deletion of Kmt2a in MN1-driven leukemia led to a downregulation of the MN1-driven leukemic program." (PMID 33542482, 2021). "This suggests a therapeutic window for inhibition of the Menin/KMT2A interaction in leukemias that rely on KMT2A." (PMID 33542482, 2021). "As expected, the group of genes we identified as the most frequent KMT2A fusion targets across our collection of samples included several genes that are known to be required for KMT2Ar leukemia, including HOXA9, MEIS1, MEF2C, MBNL1 and JMJD1C25–29." (PMID 34663924, 2021). "We identify a group of KMT2A oncoprotein target genes that are shared in the majority of KMT2Ar leukemias but are missed in a subset of samples." (PMID 34663924, 2021). "We also interrogated a gene set defined as genes bound by Menin which exhibit displacement of Menin and transcriptional downregulation upon pharmacologic inhibition of the Menin/KMT2A interaction in a human KMT2A-MLLT3 leukemia cell line." (PMID 33542482, 2021). "The aim of this study was to identify novel candidate compounds that selectively target KMT2A-rearranged (KMT2A-r) leukemia cells." (PMID 35127484, 2021). "WSS is caused by variants in the KMT2A (Lysine Methyltransferase 2A, also known as MLL, OMIM #159555) gene, which is also implicated in the disease of leukemia." (PMID 34469078, 2021). "SID7969543 preferentially inhibited the growth of a subset of KMT2A-r leukemia cells, which included various subtypes with different KMT2A translocations." (PMID 35127484, 2021). "Their data showed that the efficiency of KMT2A-ENL driven AML initiation changed with age and peaked shortly after birth, thus demonstrating that developmental context plays an important role in shaping the genetic landscape of KMT2A driven leukemias." (PMID 33668444, 2021).
leukemia (continued). "The strong overlap between genes downregulated upon inactivation of Kmt2a and inactivation of Men1 supports that the effect of Menin/Kmt2a inhibition in MN1-driven leukemias is a result of disrupting the Kmt2a complex." (PMID 33542482, 2021). "In our collection of leukemia samples, we observed both H3K4me3 and H3K27me3 at some promoters that were called as KMT2A fusion protein targets (left)." (PMID 34663924, 2021). "Automated and single-cell CUT&Tag is used to characterize the effects of KMT2A fusion proteins on chromatin in human primary leukemia samples, identifying oncogenic networks and fusion-specific therapeutic vulnerabilities." (PMID 34663924, 2021). "The first molecular evidence for a prenatal origin of childhood leukemia arose from twin studies of KMT2A-rearranged and ETV6/RUNX1 leukemia published in the 1990s." (PMID 33968846, 2021). "Patients whose leukemias harbor a rearrangement of the Mixed Lineage Leukemia (MLL/KMT2A) gene have a poor prognosis, especially when the disease strikes in infants." (PMID 35127484, 2021). "In contrast, Menin/KMT2A inhibition is effective in disrupting KMT2A dependent transcription in leukemia models that exhibit a dependency on KMT2A by preventing recruitment of the Menin/wild type KMT2A complex to a subset of target genes." (PMID 33542482, 2021). "For comparison, we also profiled KMT2A localization in untransformed human CD34+ hematopoietic stem and progenitor cells (HSPCs), in H1 human embryonic stem cells and in the K562 leukemia cell line, each of which lacks KMT2A translocations." (PMID 34663924, 2021). "Our single-cell profiling reveals that some leukemias display both active and repressive chromatin states at KMT2A fusion target loci that differ among individual cells." (PMID 34663924, 2021). "We previously established that aberrant gene expression in MN1-driven leukemia was under the control of wild type Kmt2a." (PMID 33542482, 2021). "Rearrangements involving KMT2A (KMT2Ar, previously mixed lineage leukemia, MLL) gene located at 11q23.3, account for 15–20% of pediatric AML." (PMID 34204358, 2021). "KMT2A rearrangements are a prototypical example of leukemia driven by deregulation of the epigenetic process, which disrupt the normal function of KMT2A by a fusion protein partner." (PMID 34943855, 2021). "MN1-transformed Kmt2a SET−/− CMP were able to induce leukemia with the same latency as wild type controls (median survival of 31 days in Kmt2a SET−/− versus 29 days in controls, p = ns)." (PMID 33542482, 2021). "Menin was found to be essential for transformation and maintenance of KMT2A-rearranged leukemias and our previous findings suggest that endogenous Kmt2a is required for MN1-driven leukemia." (PMID 33542482, 2021). "Recurrent chromosomal translocations involving the KMT2A gene initiate aggressive forms of leukemias and are often refractory to conventional treatments with a dismal prognosis." (PMID 34683144, 2021). "We previously found that loss of Kmt2a led to downregulation of the aberrant “MN1-driven leukemic program”, suggesting that the aberrant expression of Hoxa9 and Meis1 in MN1-driven leukemia remained under the control of its physiologic regulator, Kmt2a." (PMID 33542482, 2021). "Using AutoCUT&Tag to profile histone modifications in leukemia samples, we identified frequent KMT2A fusion oncoprotein sites with bivalent chromatin features." (PMID 34663924, 2021). "Two classes of small molecule inhibitors have emerged as possible therapies for KMT2A-rearranged leukemia: Disruptor of telomeric silencing 1-like (DOT1L) inhibitors and menin inhibitors." (PMID 32050659, 2020). "A great number of molecular strategies were designed for the treatment of KMT2A-related leukemias; however, progress has also been made in other KMT-related cancers in recent years." (PMID 33302406, 2020).
leukemia (continued). "KMT2A rearrangements are found in several groups of leukemia patients: Infantile ALL, AML, and acute megakaryoblastic leukemia (AMKL), a rare subtype of AML that occurs mainly in children with Down syndrome." (PMID 32050659, 2020). "The structure and biological functions of the KMT2A protein has been deeply investigated in leukemia, however, very few studies have explored the functions of KMT2A in malignant cervical cancer." (PMID 32436862, 2020). "HOX genes are also upregulated in leukemias with a rearrangement of the Mixed Lineage Leukemia (MLL) gene (also known as Lysine Methyltransferase 2A or KMT2A)." (PMID 32545659, 2020). "Several studies have demonstrated the potential use of KMT2A inhibitors as promising targeted therapies for KMT2A-rearranged leukemia." (PMID 32727569, 2020). "11q23 chromosomal translocations fusing the mixed lineage leukemia (MLL) gene (official gene symbol: KMT2A) with any one of >60 partners lead to aggressive leukemias with poor prognosis." (PMID 32719792, 2020). "KMT2A, known as myeloid/lymphoid or mixed-lineage leukemia (MLL), is a well-recognized leukemia-related gene and is rearranged in approximately 75% of infants with B-ALL, particularly in those less than 6 months of age." (PMID 32164600, 2020). "The mixed leukemia lineage (MLL) gene (also termed KMT2A), is frequently disrupted in AML by different chromosomal rearrangements involving other partner chromosomes." (PMID 33013836, 2020). "Identification of sarcomas with pathogenic KMT2A fusions raises a possibility of targeted therapies which are actively being pursued in KMT2A-rearranged leukemias." (PMID 32461620, 2020). "Chromosomal rearrangements of the mixed lineage leukaemia (MLL, also known as KMT2A) gene on chromosome 11q23 are amongst the most common genetic abnormalities observed in human acute leukaemias." (PMID 32549410, 2020). "KMT2A-PTD alone appears insufficient to cause AML and additional genetic hits are required for the development of KMT2A-PTD leukemia." (PMID 32231866, 2020). "The relationship between KMT2 complexes and oncogenesis was first demonstrated by the example of KMT2A, which is translocated to other fusion gene partners in approximately 10% of human leukemias." (PMID 33302406, 2020). "The mixed-lineage leukemia (MLL) gene (now renamed as Lysine-specific MethylTransferase 2A (KMT2A)) on chromosome 11q23 is disrupted in a particularly aggressive subtype of leukemias." (PMID 32260549, 2020). "We firstly cloned several individual sgRNAs targeting the equivalent introns of Kmt2a and Mllt1 that are orthologue regions in the human leukemia translocation." (PMID 33134860, 2020). "It is of interest that DOT1L can also be targeted in the leukemias devoid of KMT2A rearrangements —or, even, in the KMT2-unrelated solid tumors—to suppress the proliferation and metastasis of breast cancer cells." (PMID 33302406, 2020). "Rearrangements of the mixed-lineage leukemia (MLL) or lysine methyltransferase 2A (KMT2A) gene with over 100 known partner genes like ALL1-fused gene from chromosome (AF) 4 or AF9 are frequently found in leukemia with a dismal prognosis." (PMID 32456310, 2020). "Post-mortem examination of Kmt2a-Mllt1 mice confirmed the development of leukemia with predominant myeloblasts in the peripheral blood, splenomegaly and extensive infiltration of leukocytes into peripheral organs such as liver and kidneys." (PMID 33134860, 2020). "Haematological malignancies harbouring rearrangements of the KMT2A gene represent a unique subtype of leukaemia, with biphenotypic clinical manifestations, a rapid and aggressive onset, and a generally poor prognosis." (PMID 32721124, 2019). "The chromosomal rearrangements of the mixed-lineage leukemia gene MLL (KMT2A) have been extensively characterized as a potent oncogenic driver in leukemia." (PMID 31253180, 2019). "The blasts of KMT2A-rearranged leukemia are commonly regarded as being derived from an immature precursor." (PMID 31807115, 2019).